AQP3 (aquaporin 3 (Gill blood group))
Description:
Aquaglyceroporins form homotetrameric transmembrane channels, with each monomer independently mediating glycerol and water transport across the plasma membrane along their osmotic gradient. Could also be permeable to urea (By similarity). Also participates in cell permeability to H2O2 and H2O2-mediated signaling. In skin, transports glycerol to the epidermis and stratum corneum, where it maintains hydration, elasticity, and supports lipid biosynthesis for barrier repair (By similarity). In kidney, contributes to the reabsorption of water, helping the body maintain proper fluid balance (By similarity).
Synonyms: AQP-3; GIL
Tractability: Antibody: UniProt places it where antibodies can reach, with high confidence; its Gene Ontology location is reachable by antibodies, with high confidence; UniProt predicts a signal peptide or a membrane-spanning region; the Human Protein Atlas places it where antibodies can reach. PROTAC: ubiquitination databases record sites on it.
Gene: Protein-coding gene on chromosome 9 (33,441,156 to 33,447,596, reverse strand). Ensembl gene ENSG00000165272.
Subcellular location: Cell membrane; Basolateral cell membrane
Subcellular location (Human Protein Atlas): Plasma membrane
Pathways (Reactome):
Transport of small molecules: Passive transport by Aquaporins; Vasopressin regulates renal water homeostasis via Aquaporins
Developmental Biology: Differentiation of Keratinocytes in Interfollicular Epidermis in Mammalian Skin
Gene Ontology:
Molecular function: glycerol channel activity; identical protein binding; protein binding; water channel activity; urea transmembrane transporter activity; channel activity
Biological process: cellular response to hypoxia; glycerol transmembrane transport; odontogenesis; positive regulation of immune system process; response to retinoic acid; water transport; regulation of keratinocyte differentiation; renal water homeostasis; response to calcium ion; response to vitamin D; transmembrane transport; urea transmembrane transport
Cellular component: cell-cell junction; cytoplasm; plasma membrane; basolateral plasma membrane; membrane
Genetic constraint (gnomAD): Loss-of-function variants: 15 observed, 27.58 expected, observed/expected ratio (o/e) 0.54, 90% interval 0.36 to 0.84. The upper end of that interval is the gene's LOEUF score, 0.84, which puts it in group 3 of 6, group 1 being the genes least tolerant of losing a copy. Missense variants: 269 observed, 384.06 expected, observed/expected ratio (o/e) 0.7, 90% interval 0.63 to 0.77. Synonymous variants: 153 observed, 162.35 expected, observed/expected ratio (o/e) 0.94, 90% interval 0.82 to 1.08.
Homologues: Orthologues: chimpanzee AQP3 (99% identical), macaque AQP3 (97% identical), dog AQP3 (96% identical), guinea pig AQP3 (96% identical), mouse Aqp3 (96% identical), rabbit AQP3 (96% identical), rat Aqp3 (94% identical), pig AQP3 (93% identical), tropical clawed frog aqp3 (78% identical), zebrafish aqp3a (66% identical), zebrafish aqp3b (66% identical), Drosophila melanogaster Eglp4 (22% identical), and 3 more. Paralogues in human: AQP10 (47% identical), AQP9 (46% identical), AQP7 (45% identical), AQP7B (42% identical), AQP2 (25% identical), AQP5 (24% identical), MIP (24% identical), AQP6 (23% identical), AQP8 (23% identical), AQP1 (22% identical), AQP4 (22% identical).
Diseases named in the same sentence as AQP3 in open-access papers:
AQP3 is named in the same sentence as 244 diseases in open-access papers, as found by Europe PMC text mining. Sharing a sentence is not in itself a finding about the gene and the disease. The quoted sentences say what the papers report.
gastric cancer (54 papers, 2011 to 2025). A primary or metastatic malignant neoplasm involving the stomach. "Recent data revealed that the upregulation of AQP3 expression is paralleled with EMT-associated proteins resulting in a poor prognosis of gastric cancer." (PMID 39857360, 2024). "In human stomach cancer cells, up-regulation of AQP3 was associated with the increased expression of MMP2 and MMP9." (PMID 37143707, 2023). "AQP3 overexpression in human gastric cancer cells is associated with an increase in the level of phosphorylated GSK3β inactive form, resulting in a rise of nuclear β-catenin." (PMID 33924772, 2021). "Taken that in gastric cancer APQ3 is significantly higher than in normal gastric mucosa and was correlated to EMT proteins in gastric cancer tissues, overexpression of AQP3 is linked to poorer prognosis of these patients." (PMID 33947079, 2021). "A study showed that AQP3 and 5 expressed in higher levels in gastric carcinomas than the normal mucosa were associated with lymph node metastasis and lymphovascular invasion." (PMID 33796134, 2021). "More interestingly, another study showed that AQP3 in gastric cancer cells caused apoptosis in gastric cancer cells by downregulating cellular glycerol intake and inhibiting downstream adipogenesis." (PMID 32331274, 2020). "In gastric cancers, the expression of AQP3 has been shown to be positively associated with lymph node metastasis, low histological classification and lymphovascular invasion." (PMID 30781816, 2019). "Previous study has shown that AQP3 expression was highly associated with gastric cancer compared with normal cells, aggravating carcinogenesis and progression with lymph node metastasis and lymphovascular invasion." (PMID 29678898, 2018). "Knockdown of AQP3 expression for instance has been shown to be associated with increased migration and proliferation of gastric cancer cell lines." (PMID 23043286, 2012). "Knockdown of AQP3 for instance has been shown to be associated with increased migration and proliferation of gastric cancer cells." (PMID 23043286, 2012). "In our previous work, we showed a differential expression of AQPs between human gastric carcinomas and corresponding normal tissue, and the association of AQP3 expression with the lymph node metastasis and lymphovascular invasion of human gastric carcinoma." (PMID 21943213, 2011). "Similarly, AQP3 deficiency leads to glycerol uptake reduction and decreased energy and lipid production, thereby impairing the proliferation in gastric cancer cells." (PMID 38089478, 2023). "In addition, AQP3 deficiency can cause proliferation disorders and metabolic inhibition in gastric cancer cells." (PMID 32331274, 2020). "Moreover, latent membrane protein 2A (LMP2A) induced the phosphorylation of ERK, which thereby activated DNMT3a transcription and induced loss of AQP3 expression through CpG island methylation of AQP3 promoter in Epstein-Barr virus-associated gastric carcinoma." (PMID 38089478, 2023). "Consistently, some clinical studies also suggested that the aberrant AQP3 expression may be strongly associated with tumor progression and prognosis in several malignant cancers, including hepatocellular carcinoma, colorectal carcinoma, and gastric cancer." (PMID 34708074, 2021). "However, AQP3 reactivity in both normal gastric mucosa and gastric cancer tissues was markedly associated with H. pylori infection (p = 0.000), indicating that AQP3 may be involved in H. pylori infection-related gastric diseases." (PMID 23152856, 2012). "Poor prognosis for gastric cancer is predicted by epithelial mesenchymal transition (EMT) related proteins controlled by AQP3." (PMID 38336645, 2024). "In vitro, AQP3 also endorses the proliferation, invasion, and migration of gastric cancer cells through the PI3K/AKT/SNAIL signaling pathway." (PMID 38336645, 2024). "Upregulation of AQP3 increased the development of SGC7901 and MGC803 gastric cancer cells, but inhibiting endogenous AQP3 inhibited growth." (PMID 38336645, 2024).
gastric cancer (continued). "In gastric cancer, AQP3 induced EMT by modulating the expression of known EMT markers, including vimentin and β-catenin." (PMID 39857360, 2024). "Even more, in gastric cancer cell lines, AQP3 overexpression upregulated matrix metalloproteinases MT MMP1, MMP2, and MMP9, while its silencing decreased them via a PI3K/Akt-dependent manner." (PMID 37175840, 2023). "For example, SP1 activated LINC00659 in gastric cancer, promoting tumor progression by miR-370/aquaporin 3 (AQP3) axis." (PMID 37686205, 2023). "Our previous studies found that AQP3 promotes the invasion and metastasis of gastric cancer cells by regulating epithelial mesenchymal transformation." (PMID 35957833, 2022). "Impaired glycerol transport and lipid synthesis due to AQP3 knockdown promoted apoptosis and inhibited the proliferation of gastric cancer cells, AQP3-facilitated glycerol, a major source of ATP, participates in epidermal proliferation and tumor formation." (PMID 35972604, 2022). "miR-874 has been reported to target AQP3 in gastric cancer (GC), pancreatic ductal adenocarcinoma (PDAC) and non-small cell lung cancer (NSCLC)." (PMID 35187089, 2022). "AQP3 gave rise to chemoresistance to cisplatin in gastric cancer and facilitated chemoresistance to arsenite in melanoma." (PMID 35972604, 2022). "AQP3 levels are increased in gastrointestinal tumors; conversely, AQP3 knockdown decreased the invasiveness of gastric cancer cells." (PMID 35163313, 2022). "Research has demonstrated that silencing AQP3 contributes to proliferation impairment and apoptosis via decreased glycerol uptake and lipid synthesis in gastric cancer cells." (PMID 35972604, 2022). "H. pylori infection augments AQP3 expression to accelerate production of proinflammatory cytokines in the pathogenesis of gastric carcinoma." (PMID 35538066, 2022). "High hazard ratios for gastric cancer patients correlated with increased AQPs 2, 8 and 10 expression, contrasting with a reduced hazard ratio seen when AQP3 or AQP9 levels were increased." (PMID 32679804, 2020). "Consistent with the findings in gastric cancer, miR‐874 targeted AQP3 through directly binding to the 3′‐UTR of AQP3 mRNA, and miR‐874 regulated the expression of AQP3 in NSCLC." (PMID 32301290, 2020). "The promotive role of AQP-3 on tumor growth of gastric cancer depends on epithelial–mesenchymal transition." (PMID 33209198, 2020). "In this report, HPA database outcomes suggested markedly increased AQP3 protein expression in normal gastric tissue, and as well as in gastric cancer tissue." (PMID 29678898, 2018). "Intriguingly, we detected strong expression of AQP3 protein both in normal and gastric cancer tissues." (PMID 29678898, 2018). "AQP3 regulates gastric cancer cell proliferation, invasion and migration through the PI3K/AKT/SNAIL signaling pathway in vitro." (PMID 30555637, 2018). "For example, miR-874 inhibits cell proliferation, migration, and invasion by targeting AQP-3 in gastric cancer." (PMID 29103082, 2018). "H. pylori infection also stimulates the AQP3 level dependent production of proinflammatory cytokines IL-6, IL-8, and TNFα, which adds up to the progression of gastric carcinomas." (PMID 30555637, 2018). "AQP3 promotes stem-like properties of human gastric carcinoma cells by activating the Wnt/GSK-3β/β-catenin signaling pathway." (PMID 30555637, 2018). "Elevated AQP3 expression was also associated with CD44 expression and activation of the β-catenin signaling pathway in human gastric carcinoma specimens." (PMID 30555637, 2018). "AQP3 knockout mice were resistant to skin tumor formation and overexpression correlated with metastasis and poor prognosis in patients with breast or gastric cancer." (PMID 28991174, 2017). "AQP3 overexpression enhanced the proliferation of gastric cancer cells SGC7901 and MGC803 while silencing of endogenous AQP3 decreased proliferation." (PMID 28991174, 2017).
gastric cancer (continued). "Collectively, our results demonstrate that AQP3 facilitates cisplatin resistance in gastric cancer cells via autophagy." (PMID 27867537, 2016). "AQP3 expression is higher in human gastric cancer tissue compared with that in normal tissue, as well as in the human gastric carcinoma cell lines by Western blotting analysis." (PMID 27589719, 2016). "Altering the AQP3 expression had pronounced effects on the tumorigenic potential and self-renewal capacity of the gastric cancer cell lines SGC7901, MGC803, and AGS, both in vitro and in vivo." (PMID 26918728, 2016). "In this study, we showed for the first time that AQP3 mediates chemoresistance in gastric cancer cells to cisplatin, enhances autophagy of gastric cancer cells and the lysosome inhibitor chloroquine reverses the chemoresistance induced by AQP3." (PMID 27867537, 2016). "The involvement of AQP3 in carcinogenesis and the progression of gastric carcinoma can be due to upregulation of AQP3, which promotes the proliferation, migration and invasion of human gastric carcinoma cells." (PMID 27589719, 2016). "It seemed that both the ERK and PI3K/AKT signaling pathways were involved in the upregulation of AQP3 expression, which was induced by hyperglycemia in human gastric carcinoma." (PMID 27589719, 2016). "The present results point toward the key role of AQP3 in the tumorigenesis and progression of gastric carcinoma, and provide promising new avenues for the development of therapeutic strategies for treating gastric cancer." (PMID 26918728, 2016). "Our previous studies have established a role for AQP3 in gastric carcinogenesis and gastric carcinoma progression." (PMID 26506416, 2015). "AQP3 and AQP5 are upregulated in gastric carcinoma, and are associated with lymph node metastasis and lymphovascular invasion." (PMID 24918928, 2014). "Western blot assays and RT-PCR were used to evaluate the change of AQP3 in the human gastric cancer AGS and SGC7901 cell lines after co-culture with H. pylori." (PMID 23152856, 2012). "Our previous studies indicated that AQP3 plays an important role in the tumor growth and spread of human gastric carcinoma." (PMID 23152856, 2012). "In vitro experiments were performed to investigate the effects of H. pylori infection on AQP3 expression in human gastric carcinoma cells." (PMID 23152856, 2012). "We provide further evidence that the ERK signaling pathway is also involved in H. pylori-regulated AQP3 expression in human gastric carcinoma cells." (PMID 23152856, 2012). "To investigate the effect of H. pylori infection on AQP3 and the role of AQP3 in H. pylori infection, we performed an in vitro experiment using gastric carcinoma cells co-cultured with H. pylori." (PMID 23152856, 2012). "Then, we demonstrated that AQP3 played a critical role in gastric cancer cell migration and proliferation in previous study." (PMID 21943213, 2011). "Here, we reported that AQP3 positively regulated MMPs proteins expression through PI3K/AKT signal pathway in human gastric carcinoma cells." (PMID 21943213, 2011). "miR-185 regulates AQP3 and AQP5 expression, exerting its therapeutic effect by compromising squamous cell carcinoma and colorectal cancer progression, whereas miR-877 can suppress AQP3 in gastric cancer, promoting apoptosis and reducing cell proliferation, invasion and EMT." (PMID 39941100, 2025). "Conversely, Helicobacter pylori (H. pylori) infection, which promotes the generation of proinflammatory interleukins, significantly upregulates AQP3 expression by stimulating HIF-1α and ROS in gastric cells, linking H. pylori infection to increased AQP3 expression and gastric cancer development." (PMID 39857360, 2024). "For instance, miR-877 downregulates AQP3 to retard gastric cancer progression." (PMID 38955795, 2024). "Mechanistically LINC00659 competes with miR-370 to increase AQP3 expression in gastric cancer." (PMID 37681902, 2023).
gastric cancer (continued). "For example, miR-877 inhibits progression of gastric cancer by down-regulating AQP3, and miR-125b induces bone marrow and B-cell leukemia by inhibiting IRF4, indicating that many up-regulated miRNAs in CML samples may inhibit the expression of target genes." (PMID 37024911, 2023). "This was true since LMP2A could downregulate AQP3 by inhibiting mTOR signaling pathway to promote autophagy of gastric cancer cells." (PMID 38089478, 2023). "In human gastric cancer cell lines, AQP3 induced expression of MT1-MMP, MMP2 and MMP9." (PMID 37681917, 2023). "Notably, microRNA-874 inhibited AQP3 expression by binding to the UTR of AQP3 mRNA in gastric cancer cells, and suppressed proliferation, migration and invasion for tumorigenesis." (PMID 38089478, 2023). "Similarly, miR-877 has been found to be negatively correlated with AQP3 mRNA expression in gastric cancer tissues, and targeting AQP3 through microRNA-877 would suppress gastric cancer development and progression." (PMID 38089478, 2023). "Loss of the water channel AQP3 can enhance the tolerance of CML cells to arsenic trioxide, and high expression of AQP3 promotes the development of several cancers such as breast and gastric cancer." (PMID 37024911, 2023). "Interestingly, AQP3 silencing inhibited cell viability and autophagy in gastric cancer cells while AQP3 overexpression activated autophagy via Krüpper like factor 5 as confirmed by chromatin immunoprecipitation and dual luciferase reporter assays." (PMID 38089478, 2023). "Furthermore, enhanced expression of AQP3 was also correlated with lymph node metastasis in patients with colon and gastric cancer." (PMID 35972604, 2022). "miR-877 inhibits cell progression by downregulating AQP3 in gastric cancer." (PMID 35756697, 2022). "In addition to AQP1, AQP3 is also related to cell proliferation giving correlation of AQP3 overexpression and increased proliferation of gastric cancer cells SGC7901 and MGC803, while its downregulation had the opposite effect." (PMID 33947079, 2021). "Inactivation of ERK was involved in AQP-3 silence-suppressed gastric carcinoma cells growth." (PMID 33209198, 2020). "The ROS-HIF-1α-AQP3-ROS loop may thus be an important factor leading to the development of gastric cancer." (PMID 30781816, 2019). "The ROS-HIF-1α-AQP3-ROS loop may be an important factor leading to the development of gastric cancer." (PMID 30781816, 2019). "AQP3 overexpression in gastric cancer cells facilitates cisplatin resistance via autophagy suggesting that the development of AQP3 based tumor therapeutics could play a key role in future gastric cancer treatment strategies." (PMID 30555637, 2018). "Similarly, high expression of AQP3 and AQP9 mRNA revealed improved OS in female patients, whereas AQP0, AQP1, AQP6/2L and AQP8 were associated with poor OS in gastric cancer." (PMID 29678898, 2018). "Gastric Cancer tissues express higher levels of AQP3 compared to normal gastric mucosa." (PMID 30555637, 2018). "AQP3 is frequently studied aquaporin subtype in gastric cancer patients." (PMID 29678898, 2018). "Interestingly, AQP3 overexpression positively regulated the levels of membrane type 1-matrix metalloprotease (MT1-MMP), MMP2 and MMP9, while AQP3 knockdown resulted in reduced levels in SCG7901 human gastric cancer cells." (PMID 28991174, 2017). "Additionally, a recent study has shown that AQP3 promotes the tumorigenic potential of several gastric cancer cell lines by activating the Wnt/GSK-3β/β-catenin pathway." (PMID 27589719, 2016). "AQP3 has been found to be upregulated in gastric carcinoma tissues." (PMID 26506416, 2015). "In the future, we propose to elucidate the exact role of AQP3 in GIM malignant transformation by performing an animal experiment with Helicobacter pylori-induced gastritis or gastric carcinoma models, as well as a prospective, randomized, multicenter clinical trial." (PMID 26506416, 2015).